ETFDH (electron transfer flavoprotein dehydrogenase)
Diseases named in the same sentence as ETFDH in open-access papers (continued):
Sharing a sentence is not in itself a finding about the gene and the disease.
polycystic kidney (1 paper, 2025). "And we clarify the pathogenic mechanism of polycystic kidney caused by the loss of function of the ETFDH gene through in vitro experiments." (PMID 40075430, 2025). "Although it has been reported in many literatures that the mutation of ETFDH gene will lead to polycystic kidney phenotype, the pathogenesis is still unclear." (PMID 40075430, 2025). "We believe that the ETFDH gene is closely associated with the onset and progression of polycystic kidney disease." (PMID 40075430, 2025). "The genotype-phenotype correlation analysis establishes ETFDH as a pivotal pathogenic driver in polycystic kidney disease progression." (PMID 40075430, 2025). "The significance of this study is to expand the spectrum of pathogenic variants of ETFDH gene and demonstrate the pathogenic mechanisms by which ETFDH gene deletion leads to the development of polycystic kidney disease." (PMID 40075430, 2025). "In summary, we hypothesize that loss of function of ETFDH gene may lead to polycystic kidney by upregulating ZNF267 expression." (PMID 40075430, 2025). "Based on this study and relevant literature, we propose that the functional loss of ETFDH gene may be closely associated with the onset and progression of polycystic kidney disease." (PMID 40075430, 2025). "Literature review revealed multiple nonsense, splicing, or frameshift mutations in the ETFDH gene, which typically severely impair the structure and function of ETFQO, as reported in neonatal-onset MADD with polycystic kidney." (PMID 40075430, 2025). "The significance of this study is to reveal that ETFDH gene may be a key regulatory gene in the development of polycystic kidney." (PMID 40075430, 2025). "Based on the clinical phenotypes of the reported cases, we propose that when c.487 + 2 T > A or c.1395 T > G occurs in compound heterozygosity with other splicing or nonsense mutations in the ETFDH gene, it is highly likely to result in fetal-onset MADD with polycystic kidney disease." (PMID 40075430, 2025). "A summary of the literature on ETFDH gene mutations associated with MADD and polycystic kidney disease includes 17 mutation sites, consisting of 6 missense mutations and 11 nonsense and frameshift mutations, the latter of which lead to premature termination of protein translation." (PMID 40075430, 2025). "The functional role of ETFDH and ZNF267 in polycystic kidney diseases remains unknown, which opens up new avenues for research into the pathogenesis of polycystic kidney disease and tumors." (PMID 40075430, 2025).
rectum cancer (1 paper, 2024). "Therefore, in our study, we conducted a detailed investigation into the three drug targets of metformin (ETFDH, GPD2, and PRKAB1), and the discovery cohorts and integrated results revealed that GPD2 has an inhibitory effect on the occurrence of rectum cancer." (PMID 38504335, 2024).
respiratory distress syndrome (1 paper, 2025). "ETFDH and SURF1 were prioritized due to their known roles in mitochondrial function and their relevance to the patient’s clinical features, including respiratory distress syndrome alongside HCM." (PMID 40634996, 2025).
serine deficiency (1 paper, 2021). "Here, the clinical and biochemical investigations indicate that ETFDH:p.Pro227Thr and PHGDH:p.Ser407Pro variants likely underlie the pathogenesis of GA-II and serine deficiency, respectively." (PMID 34066864, 2021). "Several mutations of ETFDH and PHGDH genes have been associated with different forms of GA-II and serine deficiency, respectively." (PMID 34066864, 2021).
tumor (8 papers, 2022 to 2026). "RNA transcriptomic analysis showed a gene significantly associated with the low cytoplasmic S100A2 group (AKT3, TAGLN, MYLK, FGD6 and ETFDH), which correlated with tumour development and progression." (PMID 37476187, 2023). "The expression of ALDH6A1 and ETFDH was downregulated in tumor samples, and the remaining ten genes were upregulated in tumor samples as compared with normal samples." (PMID 36105252, 2022). "Furthermore, tumor differentiation status appears to influence ETFDH expression patterns, with significantly lower levels observed in poorly differentiated HCC compared to moderately and well-differentiated counterparts." (PMID 40075430, 2025). "The expression levels of ACADL, ACADS, ACADSB, ALDH6A1, ETFDH, and GCDH were found to be lower in tumor samples compared to normal samples, whereas the expression levels of CCNB1 and CDK1 were observed to be higher in tumor than in normal samples." (PMID 37994323, 2023). "Collectively, these findings reveal that while ETF insufficiency is rare and has detrimental effects in non-malignant tissues, it is common in neoplasia, where ETFDH downregulation leads to bioenergetic and signaling reprogramming that accelerates neoplastic growth." (PMID 42085321, 2026).
metabolic disorder (6 papers, 2014 to 2025). "Mutations in the gene (electron transfer flavoprotein dehydrogenase (ETFDH)) coding for this protein are responsible for multiple acyl‐CoA dehydrogenase deficiency (MADD), also known as glutaric acidemia type II (GAII) (OMIM#231680), a recessive autosomal metabolic disorder." (PMID 40688386, 2025). "No additional genetic variants associated with metabolic disorders that cause increased C8 levels, such as mutations in the ETFA, ETFB, and ETFDH genes, were identified through high-throughput sequencing, leading to a final diagnosis of MCADD." (PMID 41002789, 2025). "During subsequent follow-up, consistently elevated levels of C8 and C8/C10 were observed, and high-throughput sequencing did not reveal any additional genetic metabolic disorders associated with elevated C8 (including variations in the ETFA, ETFB, and ETFDH genes)." (PMID 41002789, 2025).
myopathy (6 papers, 2014 to 2024). A disease of the muscle in which the muscle fibers do not function properly. "In patients with muscular symptoms and histologically proven lipid storage myopathy but unremarkable metabolite patterns molecular analysis (starting with the ETFDH gene, followed by sequencing of ETFA and ETFB) is advisable." (PMID 25200064, 2014). "Muscle-specific Etfdh−/− mice develop myopathy due to CIII dysfunction, indicating that ETFDH is a required OXPHOS component and a potential therapeutic target for mitochondrial redox medicine." (PMID 38243131, 2024).
autosomal recessive disease (4 papers, 2019 to 2025). Autosomal recessive form of disease. "It is curious why some late-onset MADD patients carry single heterozygous variants in ETFDH in the context of that the disease is widely regarded as an autosomal recessive disease." (PMID 40533849, 2025). "Our data suggests a higher risk for some autosomal recessive diseases in Acadians, notably those associated with AIRE, BCHE, ETFDH, RAPSN and SLC17A5 (2 variants)." (PMID 35488281, 2022).
mitochondrial disease (3 papers, 2016 to 2024). "Secondary CoQ10 defect has already been reported in patients with mitochondrial diseases or dysfunctions including Kearns–Sayre syndrome, mtDNA depletion and PEO or mutations in ETFDH coding for electrontransferring-flavoprotein dehydrogenase and causing MADD." (PMID 26742794, 2016).
cancer (2 papers, 2026). A tumor composed of atypical neoplastic, often pleomorphic cells that invade other tissues. "In various human cancer cell lines and mouse models, ETF insufficiency caused by decreased ETFDH expression limits flexibility of OXPHOS fuel utilisation but paradoxically increases bioenergetics and accelerates neoplastic growth via activation of the mTORC1/BCL-6/4E-BP1 axis." (PMID 42085321, 2026).
infection (2 papers, 2016 to 2025). The state of being infected such as from the introduction of a foreign agent such as serum, vaccine, antigenic substance or organism. "It has been reported that ETFDH deficiency, riboflavin deficiency, and environmental or metabolic stresses (such as cold, infection, fatigue, or hunger) may together contribute to the pathogenesis of late-onset MADD." (PMID 40673202, 2025). "In summary, we demonstrated that ETF and ETFDH played a pleiotropic role in vegetative growth, conidiation and infection-related development of M. oryzae through its role in fatty acids metabolism, turgor generation and host defense response." (PMID 27113712, 2016). "Our data demonstrate that both ETF and ETFDH play an important role in vegetative growth, conidiation and infection-related development of M. oryzae through regulation of fatty acid metabolism, turgor establishment and host ROS accumulation." (PMID 27113712, 2016).
ETFDH also shares sentences with these, for which no sentence is quoted: genetic disease (4 papers); Ataxia (2); neuropathy (2); Oculomotor apraxia (2); acyl-CoA dehydrogenase deficiency (1); Adult onset (1); Anorexia (1); bacterial infections (1); brain malformations (1); cardia cancer (1); cardiofaciocutaneous (CFC) syndrome (1); chronic fatigue syndrome (1); depression (1); gastric cancer (1); glutaric acidemia IIc (1); glutaric aciduria (1); hepatocellular carcinoma (1); Hyperammonemia (1); immune dysfunction (1); intrahepatic cholangiocarcinoma (1); leukodystrophy (1); lipid metabolism disorder (1); Lipid storage disease (1); Methylmalonic aciduria (1); mitochondrial complex I deficiency (1); multisystem atrophy (1); Neonatal onset (1); sarcosinemia (1); Schaaf-Yang syndrome (1); Sensory neuropathy (1).
A further 4 diseases each share a sentence with ETFDH in 1 paper.